ENSG00000252787
Gene: Small nucleolar RNA gene on chromosome 3 (52,688,890 to 52,688,962, forward strand). Ensembl gene ENSG00000252787.
Homologues: Paralogues in human: SNORD19C (68% identical), SNORD19 (60% identical).